ENSG00000278406
Gene: Miscellaneous RNA gene on chromosome 2 (192,775,943 to 192,776,073, forward strand). Ensembl gene ENSG00000278406.
Gene Ontology:
Biological process: regulation of apoptotic process